IGF1R (insulin like growth factor 1 receptor)
Diseases named in the same sentence as IGF1R in open-access papers (continued):
Sharing a sentence is not in itself a finding about the gene and the disease.
nasopharyngeal carcinoma (12 papers, 2019 to 2024). A carcinoma arising from the nasopharyngeal epithelium. "The mechanism of IGF-1R overexpression in nasopharyngeal carcinoma cells in situ before and after the development of bone metastasis needs to be further investigated." (PMID 38342894, 2024). "We then further validated the clinical relevance of IGF-1R in a cohort of nasopharyngeal carcinoma at Nanfang Hospital of Southern Medical University." (PMID 38342894, 2024). "In the in vitro experiments, inhibition of IGF-1R in nasopharyngeal carcinoma cells inhibited cell proliferation and increased the radiosensitivity of nasopharyngeal carcinoma cells." (PMID 38342894, 2024). "In summary, these data suggest that tumor cells can induce IGF-1 secretion by osteoclasts and that osteoclast-derived IGF-1 in turn promotes the proliferation of IGF-1R-expressing nasopharyngeal carcinoma cells." (PMID 38342894, 2024). "YTHDC2 activates the IGF1R/Akt/S6 signal axis to promote radiotherapy tolerance for nasopharyngeal carcinoma." (PMID 33748145, 2021). "Recently, miR-100 has been shown to be involved in suppressing migration and invasion of nasopharyngeal carcinoma cells by targeting insulin-like growth factor 1 receptor." (PMID 31513595, 2019). "In our study, we demonstrated that nasopharyngeal carcinoma tumor cells with high IGF1-R expression have a high propensity for bone metastasis, and IGF-1 secreted by osteoclasts promotes the proliferation of tumor cells in the bone marrow through the IGF-1R/AKT/S6 signaling pathway." (PMID 38342894, 2024). "In addition, immunostaining of clinical nasopharyngeal carcinoma samples from the Nanfang Hospital of Southern Medical University cohort revealed a strong positive correlation between IGF-1R expression and phosphorylation of S6." (PMID 38342894, 2024). "In addition, IGF-1R expression was higher in patients with bone metastases from nasopharyngeal carcinoma than in primary tumors." (PMID 38342894, 2024). "Importantly, immunostaining of bone metastases from clinical nasopharyngeal carcinoma showed that IGF-1R was abundantly expressed in tumor cells and IGF-1 in microenvironmental cells." (PMID 38342894, 2024). "In addition, whether treatment targeting IGF-1R in nasopharyngeal carcinoma cells before bone metastasis occurs can effectively prevent its occurrence, which still needs further study." (PMID 38342894, 2024). "However, the exact mechanism of IGF-1R in distant metastasis of nasopharyngeal carcinoma and its therapeutic implications are unknown." (PMID 38342894, 2024). "In nasopharyngeal carcinoma, m6A reader YTHDC2 increased the translation of IGF1R, consequently activating IGF1R-AKT signaling, inhibiting tumor cell apoptosis, stimulating protein synthesis, and promoting radioresistance." (PMID 38771260, 2024). "The effects of IGF-1 neutralizing antibody, IGF-1R specific inhibitor (NVP-AEW541) and mTORC inhibitor (rapamycin) on nasopharyngeal carcinoma bone metastasis were also explored in animal experiments." (PMID 38342894, 2024). "YTHDC2 physically binds to insulin-like growth factor 1 receptor (IGF1R) mRNA to promote the translation of IGF1R mRNA, which in turn activates the IGF1-AKT/S6 signaling pathway and promotes radiotherapy resistance in nasopharyngeal carcinoma cells." (PMID 35945641, 2022). "YTHDC2 contributed to radioresistance in nasopharyngeal carcinoma (NPC) cells by binding to IGF1R mRNA and promoting the translation of the IGF1R transcript, leading to downstream activation of the IGF1R-AKT/S6 signaling axis." (PMID 33669361, 2021). "m6A modification can promote the translation of IGF1R mRNA through the YTHDC2-dependent pathway, thereby activating the IGF1R-AKT/S6 signaling pathway and leading to radiotherapy resistance in nasopharyngeal carcinoma." (PMID 33926508, 2021). "The specific high expression of IGF-1R in nasopharyngeal carcinoma tumor and low expression in normal tissue suggest the potential of IGF-1R as a therapeutic target." (PMID 38342894, 2024).
nasopharyngeal carcinoma (continued). "It is well known that nasopharyngeal carcinoma has a high sensitivity to radiation therapy, however, whether nasopharyngeal carcinoma cells with high IGF-1R expression have radiotherapy resistance is not yet clear." (PMID 38342894, 2024). "Although previous studies have reported the biological function of IGF-1R in many cancers, including nasopharyngeal carcinoma, its potential mechanism in NPC bone metastasis has not been studied." (PMID 38342894, 2024). "Furthermore, YTHDC2 has been found to be highly expressed in radiation resistant nasopharyngeal carcinoma (NPC) cells, and YTHDC2 can bind to the mRNA of IGF1R and promote its expression." (PMID 38790013, 2024). "In nasopharyngeal carcinoma (NPC), YTHDC2 increased the translation efficiency and expression of IGF1R mRNA, thereby activating the downstream PI3K-AKT/S6 pathway, inhibiting tumor cell apoptosis, stimulating protein synthesis, and promoting radiotherapy resistance." (PMID 37264402, 2023).
osteoporosis (12 papers, 2012 to 2025). A condition of reduced bone mass, with decreased cortical thickness and a decrease in the number and size of the trabeculae of cancellous bone (but normal chemical composition), resulting in increased fracture incidence. "The LASSO regression algorithm established an osteoporosis-related model, identifying six disease-related candidate core target genes (IGF1R, NR3C1, MAP3K1, BRAF, WNK4, CNR2)." (PMID 40692598, 2025). "Another study shows that calycosin plays an anti-osteoporosis effect through the IGF1R/PI3K/Akt signaling pathway." (PMID 38254101, 2024). "In patients with osteoporosis, primary osteoblasts have an impaired IGF-1R signaling decoupled from IGF-1 stimulation, which causes lower proliferation rate and differentiation and therefore bone loss." (PMID 29138637, 2017). "It has also been shown in animal experiments that IGF-1R and phosphorylation of IGF-1R were also significantly higher in OVX + streptozotocin-induced osteoporosis model rats than in normal rats." (PMID 34663464, 2021). "Our results imply that PTE promotes the proliferation and osteogenic differentiation of rBMSCs by upregulating p38 MAPK, STE20, and IGF1R and downregulating TRAF6 expression, which may provide experimental evidence of the potential of PTE in the treatment of osteoporosis." (PMID 30984279, 2019). "Additionally, this study indicates that p38 MAPK and its related genes (STE20, IGF1R, and TRAF6) are involved in the mechanism of rBMSCs' osteogenic differentiation, which provides experimental evidence of the potential application of PTE in the treatment of osteoporosis." (PMID 30984279, 2019). "Whilst administration of IGF-1 to osteoporosis patients has little positive effect on bone density, osteoblasts isolated from osteoporotic donors have an attenuated PI3K/AKT response to IGF-1, suggesting that IGF-1R responsiveness may play a role in osteoporosis." (PMID 22833734, 2012).
pancreatic ductal adenocarcinoma (12 papers, 2014 to 2025). An infiltrating adenocarcinoma that arises from the epithelial cells of the pancreas. "The proposed methodology was validated using two well-established kinases, FGFR2 and IGF1R, whose roles have been linked in various pathological conditions (e.g., pancreatic ductal adenocarcinoma, PDAC)." (PMID 40362694, 2025). "Immunohistochemical investigations have shown that insulin-like growth factor-I receptor (IGF1R) overexpression is linked to poor prognosis in patients with pancreatic ductal adenocarcinoma." (PMID 38535034, 2024). "High IGF‐1R expression in tumour cells is associated with poor outcomes in patients with resected pancreatic ductal adenocarcinoma." (PMID 34528373, 2021). "Patients with advanced pancreatic ductal adenocarcinomas and high IGF-1R to low IGFBP-3 ratio expression in the pancreas had worse overall survival rates." (PMID 37623681, 2023). "IGF-1 and insulin-like growth factor 1 receptor (IGF-1R) have been reported to be abundantly expressed in pancreatic ductal adenocarcinoma tissue." (PMID 37623681, 2023). "Taken together, these results indicate that silencing IGF-1R not only decreases migration ability, but also the invasive properties of pancreatic ductal adenocarcinoma cells." (PMID 24809702, 2014). "We examined the expression levels of IGF-1R in pancreatic ductal adenocarcinoma cell lines (HPAC, MIA PaCa-2 and PANC-1) using western blot." (PMID 24809702, 2014). "In summary, our study demonstrates that silencing IGF-1R strongly inhibits proliferation, colony forming capability, migration, and invasive/metastatic potential of pancreatic ductal adenocarcinoma cells." (PMID 24809702, 2014). "Our findings suggest that targeted therapy against IGF-1R would be effective and beneficial for treatment of patients with aggressive metastatic pancreatic ductal adenocarcinoma." (PMID 24809702, 2014). "In addition, the expression of EGFR was reported in conjunction with insulinlike growth factor 1 receptor (IGF-1R) to predict poor survival in pancreatic ductal adenocarcinoma." (PMID 27399694, 2016). "Patients with pancreatic ductal adenocarcinoma were shown to have excessive levels of IGFBP-1, 3, IGF2BP-2, IGF-1, and IGF1R in their blood and pancreatic cells." (PMID 37623681, 2023). "Consequently, the simultaneous inhibition of IGF1R, ERK, and autophagy increased the cytotoxicity in pancreatic ductal adenocarcinoma cell (PDAC) lines and reduced the human PDAC organoid survival." (PMID 36766800, 2023).
bone tumor (11 papers, 2014 to 2024). "Overall, these data suggest that blocking mTORC1 effectively inhibits IGF-1R-induced bone tumor proliferation and reduces the risk of bone metastasis." (PMID 38342894, 2024). "Notably, β-catenin showed clinical significance and positive association with primary bone tumor aggressiveness in our previous study which can emphasize the possible relation of IGF-1R and β-catenin in bone tumor pathogenesis." (PMID 36713521, 2022). "The association of IGF-1, IGFBP-1, IGFBP-3 and IGF-1R with bone cancer different features." (PMID 36713521, 2022). "More recently, TRPA1 has been shown to be a regulator of metastatic bone cancer pain via insulin-like growth factor 1 receptor (IGF-1R) signaling in Schwann cells." (PMID 37892239, 2023). "The gene expression analysis demonstrated a significant increase in the mRNA level of IGF-1R in bone tumor tissues compared to tumor margins (P < 0.0001)." (PMID 36713521, 2022). "Bone tumors expressed a significantly higher level of IGF-1R protein compared to tumor margins (P < 0.0001)." (PMID 36713521, 2022). "LGALS9, for example is a gene that produces Galactin-9, a well-studied protein expressed on tumour cells, and DMBT1 is a tumour suppressor gene involved in bone cancer that like IGF1R has been previously identified as key velvet antler peptide." (PMID 35151275, 2022). "The levels of IGF‐I and ‐II in bone were higher than those in other organs of the human body, so PCa cells with high expression of IGF1R tended to metastasize to bone and developed metastatic bone tumors." (PMID 34185427, 2021). "The simultaneous increase of IGF-1R and its associated mediators in the same set of samples in our current study can confirm the possible role of the IGF-1 axis on the change of ECM proteases in favor of bone cancer cell invasion." (PMID 36713521, 2022). "The malignant bone tumors expressed more IGF-1R protein compared to benign tumors (P < 0.0001)." (PMID 36713521, 2022). "An additional study assessing the predictive value of IGF1R surface expression in bone tumor xenograft models via antibody-labeled Immuno-SPECT imaging demonstrated that elevated surface expression IGF1R is associated with increased response to antibody-mediated therapy." (PMID 25170759, 2014).
cholangiocarcinoma (11 papers, 2009 to 2025). A carcinoma that arises from the intrahepatic biliary tree (intrahepatic cholangiocarcinoma) or from the junction, or adjacent to the junction, of the right and left hepatic ducts (hilar cholangiocarcinoma). "Studies have shown the role of IGF‐1 and IGF‐1R in regulating tumor cell growth in human cholangiocarcinoma and cholangiocarcinoma cell lines (Huh‐28, TFK‐1, MZ‐CHA‐1)." (PMID 40304434, 2025). "Then, we analyzed IGF1R expression levels in cholangiocarcinoma using data from the TCGA-CHOL database, focusing on the RTK family." (PMID 41275311, 2025). "The IGF2/IGF1R/IR axis mediates adaptive resistance to erlotinib by undergoing an IGF1R/IR phenotypic switch in cholangiocarcinoma." (PMID 34831014, 2021). "The inhibition of IR/IGF1R reduced the epithelial-mesenchymal transition and cancer stem cell-like traits in ‘resistant cells’ of cholangiocarcinoma." (PMID 32694937, 2020). "Furthermore, IGF1-driven IGF1R activation promotes tumor progression both in vitro and in vivo, while IGF1R inhibition via linsitinib effectively reduces these oncogenic effects, highlighting the significance of the PTPN9–IGF1R signaling axis in cholangiocarcinoma." (PMID 41275311, 2025). "Subsequently, to determine the appropriate cell lines for experimental validation, we examined IGF1R and PTPN9 expression in several commonly used cholangiocarcinoma cell lines and a normal biliary epithelial cell line." (PMID 41275311, 2025). "Recently was shown that CC express estrogens receptor (ER–α and –β) directly linked with insulin-like growth factor 1 (IGF1) and IGF1-R (receptor), which could represent a strategy for the management of cholangiocarcinoma." (PMID 27933122, 2009). "In cholangiocarcinoma (CCA), the interaction between cancer cells and CAFs mediated by insulin-like growth factor 2 (IGF2), insulin receptor (IR) and IGF1 receptor (IGF1R) was found to regulate ERL resistance." (PMID 30927928, 2019).
Cognitive impairment (11 papers, 2014 to 2025). Abnormal cognition is characterized by deficits in thinking, reasoning, or remembering. "For instance, ablation and/or inhibition of IGF1R from adult neurons was shown to alleviate AD pathology and associated cognitive deficits in transgenic mouse models of the disease." (PMID 33562061, 2021). "VSMC-specific knockdown of Igf1r mimics many aging-associated changes, including cognitive impairment and impaired vascular physiology, and highlights the idea that impaired VSMC function may contribute to age-related cerebrovascular decline and VCID." (PMID 38425784, 2024). "By showing that IGF-1 is an important mediator of the beneficial effect of the neural-endocrine network in TBI models, our findings place IGF-1/IGF-1R as a potential target capable of noncoding RNAs and opposing mitophagy failure and cognitive impairment in TBI." (PMID 36062186, 2022). "The functional significance of this pathway is underscored by our rescue experiments: local administration of IGF‐1 into the dorsal DG reversed both nociceptive hypersensitivity and cognitive impairment in SNI mice, with these effects abrogated by IGF‐1R antagonism or PI3K/AKT inhibition." (PMID 41414737, 2025). "Critically, pretreatment with the IGF‐1R antagonist JB‐1 (0.8 μM in 0.5 μL) or the AKT inhibitor LY294002 (0.8 μM in 0.5 μL) abolished the therapeutic effects of IGF‐1 in SNI mice, implicating IGF‐1R/AKT signaling in the observed rescue of nociceptive and cognitive deficits." (PMID 41414737, 2025). "Contrary to our finding, the down-regulation of IGF1R and its ligand IGF1 was observed in the hippocampus of rats with vascular dementia and the treatment of mice with an IGF1R agonist alleviated the white matter damage and cognitive deficits after cerebral hypoperfusion." (PMID 36771351, 2023).
Hypertension (11 papers, 2017 to 2025). The presence of chronic increased pressure in the systemic arterial system. "We used a hypertension-based model of cerebrovascular dysfunction in mice with VSMC-specific IGF-1 receptor (Igf1r) deficiency and evaluated the development of cerebrovascular pathologies and cognitive dysfunction." (PMID 38425784, 2024). "It has been suggested that increased matrix metalloproteinase (MMP) activity in hypertension results in the proteolytic cleavage of the extracellular IGF-1R alfa subunit." (PMID 38540997, 2024). "All these data indicate the critical role of the IGF-1/IGF-1R axis in PH development both in the experimental hypertension models and the adult human subjects." (PMID 38540997, 2024). "Therefore, in addition to comparing outcomes in Igf1r KD vs. control animals, we also assessed the effects of hypertension in many experiments." (PMID 38425784, 2024). "Hypertension is a major risk factor for other age-related cerebrovascular pathologies such as cerebral microhemorrhages, so we hypothesized that the additional insult of hypertension would worsen the phenotypes in our Igf1r KD group." (PMID 38425784, 2024). "We have also identified 8 important genes (NME4, PNPLA7, GGT5, PTGS2, IGF1R, NT5C2, ENTPD1 and PTEN), a number of gene ontology categories and biological pathways that may be associated with military pilot hypertension." (PMID 29996846, 2018). "Old-aged Igf1r+/− mice had increased adiposity and exhibited increased adipogenesis, indicated that reduced expression of IGF1R may have a correlation with hypertension." (PMID 29996846, 2018). "We have also identified 8 important genes (NME4, PNPLA7, GGT5, PTGS2, IGF1R, NT5C2, ENTPD1 and PTEN), a few GO categories and biological pathways that may be associated with the military pilot hypertension." (PMID 29996846, 2018). "Network pharmacology identified ten key bioactive compounds (e.g., liquiritigenin, isoliquiritigenin, and caffeic acid), 149 hypertension-related targets, and ten core targets such as SRC, PIK3CA, PIK3CB, EGFR, and IGF1R." (PMID 41155608, 2025). "Here, we studied the relationship between leukocyte IGF-1/IGF-1R mRNA, IGF-1R protein expression, plasma IGF-1 levels, and hypertension-mediated organ damage (HMOD) parameters in pediatric PH patients." (PMID 38540997, 2024). "The results from Western blotting showed that NME4 and PNPLA7 these two genes were up-regulated significantly and GGT5, PTGS2, IGF1R, NT5C2, ENTPD1 and PTEN these six genes were down-regulated significantly in PBMCs of military pilots with hypertension." (PMID 29996846, 2018). "Our behavioral assessments showed impaired cognitive performance in Igf1r KD, particularly in motor coordination and spatial learning, that were not affected by concurrent hypertension." (PMID 38425784, 2024). "One of the interesting findings from this work was that hypertension did not exacerbate the effects of Igf1r KD on autoregulation and cognition." (PMID 38425784, 2024). "Instead, novel correlations between IGF1R, IRS1, IRS2, and insulin appeared with hypertension demonstrating that IGF1 is no longer responsible for activation of intracellular processes through IGF1R." (PMID 31327319, 2019). "However, there are no data on IGF-1/IGF-1R expression in PH children/adolescents, presenting early stages of hypertension development in humans." (PMID 38540997, 2024). "However, our functional data showing physiological defects in normotensive Igf1r KD animals suggest that IGF-1 may also be important for basal maintenance of vascular wall integrity, not just for adaptive responses to hypertension." (PMID 38425784, 2024).